CHI3L2 (chitinase 3 like 2)
Diseases named in the same sentence as CHI3L2 in open-access papers (continued):
Sharing a sentence is not in itself a finding about the gene and the disease.
Alzheimer disease (4 papers, 2008 to 2024). A progressive, neurodegenerative disease characterized by loss of function and death of nerve cells in several areas of the brain leading to loss of cognitive function such as memory and language. "In recent studies, altered levels of CHIT and CHI3L2 have been observed across a spectrum of neurological disorders, including MS, Alzheimer’s disease (AD), ALS, stroke, traumatic brain injury (TBI) and Creutzfeldt–Jakob disease (CJD)." (PMID 38785530, 2024). "Chitinase 3-like 1 (CHI3L1), chitinase 3-like 2 (CHI3L2), and neuronal pentraxin II (NPTX2) are inflammatory biomarkers of Alzheimer’s disease (AD)." (PMID 32066474, 2020).
multiple sclerosis (4 papers, 2021 to 2024). A progressive autoimmune disorder affecting the central nervous system resulting in demyelination. "The IL-2:IL-6 ratio, IL-2, and chitinase 3-like 2 (all in cerebrospinal fluid) might be of value as prognostic biomarkers in early phases of multiple sclerosis." (PMID 35759479, 2022). "One control patient with multiple sclerosis displayed the highest level of CHIT1 (16,456 pg/mL), CHI3L1 (357 ng/mL) and CHI3L2 (36 ng/mL), but not pNFH (355 pg/mL)." (PMID 34359293, 2021).
amyotrophic lateral sclerosis (3 papers, 2021 to 2024). Amyotrophic lateral sclerosis (ALS) is a neurodegenerative disease characterized by progressive muscular paralysis reflecting degeneration of motor neurons in the primary motor cortex, corticospinal tracts, brainstem and spinal cord. "Previous studies showed CHI3L2 mRNA is significantly up-regulated in osteoarthritis, Alzheimer's disease, multiple sclerosis, and amyotrophic lateral sclerosis patients." (PMID 33937022, 2021). "CHI3L2 was secreted by microglia/astrocytes and could increase monocyte/macrophage infiltration, angiogenesis, and neuronal death in amyotrophic lateral sclerosis." (PMID 33937022, 2021).
depression (3 papers, 2022 to 2025). "Additional omics data and experimental approaches will be warranted to determine the regulatory mechanisms underlying CHI3L2’s differential expression, sex-specificity, and mechanistic role in the context of depression and LOAD." (PMID 36421693, 2022). "Our approach identified differential expression of CHI3L2 among depression cases that was stronger within the LOAD only cohort." (PMID 36421693, 2022). "This further suggests CHI3L2 involvement in depression in general." (PMID 36421693, 2022). "Our work may further explain this finding and provide evidence to support CHI3L2 as a marker for depression in LOAD." (PMID 36421693, 2022).
optic neuritis (3 papers, 2020 to 2024). Optic neuritis is inflammation of the optic nerve, the nerve that carries the visual signal from the eye to the brain.The conditionmay cause sudden, reduced vision in the affected eye(s). "Moreover, the increased level of CHI3L2 in patients diagnosed with optic neuritis as a first demyelinating episode was associated with poorer performance in PASAT after a 14-year follow-up period." (PMID 32444997, 2020). "Compared to HCs, elevated levels of CHI3L2 were found in the CSF of patients with optic neuritis; furthermore, patients with higher CHI3L2 levels were more likely to develop MS in the future." (PMID 35328802, 2022). "Another member of this protein family, chitinase-3-like 2 protein (CHI3L2), the closest homolog of CHI3L1, was suggested as a useful biomarker of the transition from optic neuritis to MS." (PMID 32444997, 2020).
renal cell carcinoma (3 papers, 2021 to 2022). "In renal cell carcinoma, CHI3L2 was mainly expressed in tumor cells and tumor-associated macrophages." (PMID 33937022, 2021). "CHI3L2 was suggested as a prognostic biomarker for renal cell carcinoma, predicting high risk for postoperative progression." (PMID 34395626, 2021).
virus infection (3 papers, 2021 to 2025). "Notably, CHI3L2 belongs to the chitinase-like protein family, which has been implicated in inflammatory responses and tissue remodeling, with recent study highlighting its upregulation in the context of viral infections and lung inflammation." (PMID 41463538, 2025).
Arthritis (2 papers, 2014 to 2018). Inflammation of a joint. "Arthritis can be induced in animals by immunization with different components of cartilage; collagen type II (CII), collagen type IX (CIX), and collagen type XI (CXI), proteoglycan (PG), cartilage link protein (CLP), and chitinase 3-like protein 2 (CHI3L2/YKL-39)." (PMID 29495570, 2018).
Autoimmunity (2 papers, 2020 to 2025). The occurrence of an immune reaction against the organism's own cells or tissues. "More importantly, autoimmunity against CHI3L2 was also detected in OA patients." (PMID 32842604, 2020).
Cognitive impairment (2 papers, 2020 to 2022). Abnormal cognition is characterized by deficits in thinking, reasoning, or remembering. "CHI3L2 has been linked with cognitive impairment in AD, with its inflammatory roles cited." (PMID 36421693, 2022).
ovarian carcinoma (2 papers, 2008 to 2024). A malignant neoplasm originating from the surface ovarian epithelium. "Chitinase-3-like 2 (CHI3L2), a secreted glycoprotein component of the ECM which has been linked to early detection and prognosis of ovarian cancer, was identified in this study." (PMID 18433489, 2008). "CHI3L2 appears to be downregulated in DC as opposed to increased expression seen in ovarian cancer patients." (PMID 18433489, 2008).
amyloid (1 paper, 2020). "Total numbers of amyloid plaque and NFTs did not correlate with CHI3L1, CHI3L2, GFAP, and C1q protein levels at any clinical stage." (PMID 32066474, 2020).
brain cancer (1 paper, 2010). A primary or metastatic malignant neoplasm affecting the brain. "Two similar protein families, namely the fasciclin domain containing protein TGFBI (βig-H3), and chitinase-like proteins, CHI3L1 and CHI3L2, are present in mammals, and recent Massively Parallel Signature Sequencing (MPSS) analysis show similar expression pattern in brain cancer cells." (PMID 21124849, 2010).
breast tumors (1 paper, 2024). "In our study, we found evidence that CHI3L2 expression in cancer cells is specific for this type of breast tumor." (PMID 39557919, 2024). "Our team will focus on this question in the future to clarify the mechanism of the role of CHI3L2 in the communication between TAMs and cancer cells in breast tumors, which could be a new key factor in IDC tumor progression." (PMID 39557919, 2024). "In fact, it is more likely that the source of CHI3L2 protein in breast tumor tissue is macrophages." (PMID 39557919, 2024). "Previously, CHI3L2 expression in breast tumors had only been observed in TAMs." (PMID 39557919, 2024).
dementia (1 paper, 2025). Loss of intellectual abilities interfering with an individual's social and occupational functions. "Other genes previously associated with AD or dementia were differentially expressed in both brain regions: CHI3L2, FCGBP, GLI1, STAB1, APOC1, MYO7A, and long non‐coding RNA JHDM1D‐AS1." (PMID 39876821, 2025).
glial cell tumors (1 paper, 2021). "Upregulation of CHI3L2 could increase the phosphorylation level of ERK1 and ERK2, thus inhibiting tumor cell mitosis and proliferation in glial cell tumors." (PMID 33860055, 2021).
invasive ductal breast carcinoma (1 paper, 2024). The most common type of invasive breast carcinoma, accounting for approximately 70% of breast carcinomas. "Moreover, addition of exogenous CHI3L2 protein incresed level of pERK1/2 in CHI3L2- metastatic adenocarcinoma MDA-MB-436 cells, and also in invasive ductal breast carcinoma CHI3L2- BT-474 cells." (PMID 39557919, 2024).
non-small cell lung carcinoma (1 paper, 2020). A group of at least three distinct histological types of lung cancer, including non-small cell squamous cell carcinoma, adenocarcinoma, and large cell carcinoma. "Idgf2 is a member of the conserved chitinase-like protein (CLP) family including CHI3L1/YKL-40 and CHI3L2/YKL-39 which are implicated in inflammatory diseases and a variety of cancers including colon and non-small cell lung cancer." (PMID 33370287, 2020).
triple-negative breast carcinoma (1 paper, 2021). An invasive breast carcinoma which is negative for expression of estrogen receptor (ER), progesterone receptor (PR), and human epidermal growth factor receptor 2 (HER2). "Overexpression of CHI3L2 and FES was observed in triple negative breast cancers (TNBCs) relative to other subtypes in immune‐rich tumors." (PMID 34189853, 2021).
tumor (22 papers, 2008 to 2025). "CHI3L2 is mainly secreted by tumor-associated macrophages and associated with metastasis progression and poor outcome." (PMID 38254997, 2024). "This is the first prospective study of the clinical value of CD44 and CHI3L2 SNV–based biomarkers in PDAC after tumor resection." (PMID 38635586, 2024). "Our analysis of tumor material also showed a decrease in CHI3L2 expression with higher tumor grades (G)." (PMID 39557919, 2024). "It was reported that only TGFβ, the key regulatory factor of tumor progression, was able to stimulate CHI3L2 mRNA levels in human macrophages in vitro." (PMID 33937022, 2021). "TIMER platform analysis indicated CHI3L2 expression was closely related to diverse marker genes of tumor immune infiltrating cells, including monocytes, TAMs, M1 macrophages, M2 macrophages, TGFβ1+ Treg and T cell exhaustion in GBM and LGG." (PMID 33937022, 2021). "Eomes+ Tr1 cells, characterized by expression of GZMK and CHI3L2, have been detected in the tumor microenvironment." (PMID 34880348, 2021). "The Tumor IMmune Estimation Resource (TIMER) platform was used to explore the correlations between CHI3L2 and diverse marker genes of tumor immune infiltrates." (PMID 33937022, 2021). "Our flow cytometry results further confirmed that CHI3L2 can induce CD8+ T cell apoptosis, indicating that CHI3L2 has the potential to promote tumor immune escape." (PMID 33937022, 2021). "It is possible that the overexpression of CHI3L2 in low-grade malignant tumors suggests that the protein may be involved in inhibiting tumor growth or promoting tumor growth only at early stages." (PMID 39557919, 2024). "Moreover, CHI3L2 was expressed at low levels in macrophage cells in vitro, but its expression was enhanced in co-cultures designed to mimic the tumor microenvironment and TAMs." (PMID 39557919, 2024). "In tumor material, the highest expression of CHI3L2 was observed in G1 IDC tumors, and it decreased with the progression of tumor grades." (PMID 39557919, 2024). "The results obtained show that CHI3L2 expression decreases with increasing degree of tumor grade and negative status of estrogen (ER) and progesterone receptors (PR)." (PMID 39557919, 2024). "CHI3L2 expression may be specific for cancer cells in IDC and involved in cross-talk with the tumor microenvironment." (PMID 39557919, 2024). "The expression level of CHI3L2 was highest in non-malignant breast tissue lesions (NBTLs) and decreased significantly with higher tumor grades." (PMID 39557919, 2024). "Furthermore, we observed a negative correlation between CHI3L2 expression in tumor cells and infiltration of macrophages, but not exactly TAMs." (PMID 39557919, 2024). "Higher expression of CHI3L2 was observed in tumors with lower malignancy grade or in non-malignant lesions and higher levels of CHI3L2 protein were detected in ER + and PR + tumors, which may indicate protective, anti-tumor role of this protein." (PMID 39557919, 2024). "However, chitinase-like proteins, including CHI3L1, CHI3L2 and SI-CLP (stabilin-1 interacting chitinase-like protein), have biological functions that contribute to stimulation of cell proliferation, support of angiogenesis and tumor invasion, cell interactions and immunomodulation." (PMID 39557919, 2024).
cancer (10 papers, 2010 to 2024). A tumor composed of atypical neoplastic, often pleomorphic cells that invade other tissues. "Previous studies have demonstrated the expression of CHI3L2 in cancer cells, including glioblastoma tumors and cell lines such as U-87 MG and HEK29344,45." (PMID 39557919, 2024). "The immunofluorescence reaction proves the presence of CHI3L2 in the cytoplasm of cancer cells in IDC tumors." (PMID 39557919, 2024). "Our study has shown that IDC cancer cells express the CHI3L2 protein, possibly indicating a novel function of this protein." (PMID 39557919, 2024). "In patients with glioma high levels of CHI3L2 expressed in cancer cells and on microglia cells correlated with poor prognosis." (PMID 36686729, 2022). "Actually, these CD163 and CHI3L2 have been suggested as prognostic biomarkers in other types of cancers." (PMID 34395626, 2021). "The specific function of CHI3L2 in the interaction between cancer cells and macrophages remains unclear at this moment." (PMID 39557919, 2024). "Cytoplasmic expression of CHI3L2 in cancer cells in IDC was detected by immunohistochemistry." (PMID 39557919, 2024). "Results from a GeneMANIA database analysis showed that PLCG2, CHI3L2, SH2D2A, and NLRP3 and 20 other proteins formed a complex network of which 12 genes were enriched in cancer-related pathways." (PMID 31993418, 2019). "Macrophages expressed CHI3L2 at low levels, but the expression of this protein was higher in macrophage cocultures with conditioned medium from CHI3L2-negative cancer cells (MCF-7 and MDA-MB-468), and also with CHI3L2-positive MDA-MB-231 cells." (PMID 39557919, 2024). "Interestingly, in our simple co-culture model, CHI3L2-negative cancer cells were found to stimulate macrophage production of this protein, whereas CHI3L2-positive normal breast epithalial cells not." (PMID 39557919, 2024).
infection (5 papers, 2012 to 2020). The state of being infected such as from the introduction of a foreign agent such as serum, vaccine, antigenic substance or organism. "In this study, the expression of a chitinase-3-like protein 2 gene (CHI3L2) negatively associates with infection." (PMID 33017218, 2020).
neurodegenerative disease (3 papers, 2022 to 2024). A disorder of the central nervous system characterized by gradual and progressive loss of neural tissue and neurologic function. "CHIT, CHI3L1, and CHI3L2 have received significant attention from both clinical and biological perspectives concerning inflammation-prone brain diseases, and they are now recognized as markers of neuroinflammation across a spectrum of neurodegenerative diseases." (PMID 38785530, 2024).
neurological diseases (3 papers, 2021 to 2024). "Indeed, while the levels of CHI3L1 and CHI3L2 in AD patients tend to increase leading to hypothesis of a potential immunological role, CHID1 levels tend to decrease both with age and in neurological diseases such as AD." (PMID 33924468, 2021).
bacterial infection (2 papers, 2020 to 2025). "The four CHIA, CHI3L2, PRDM2 and KDM5B genes that we identified on BTA4 and 16 in the Swedish Red Cattle were previously reported as disease resistance genes (i.e. to gastrointestinal nematodes or bacterial infection) in independent studies on sheep and cattle breeds." (PMID 32887549, 2020).
CHI3L2 also shares sentences with these, for which no sentence is quoted: rheumatoid arthritis (5 papers); coccidiosis (2); schizophrenia (2); Stroke (2); atherosclerosis (1); autism (1); autoimmune disease (1); avian flu (1); brain diseases (1); colon cancer (1); colorectal cancer (1); demyelinating disease (1); fibrocystic disease (1); gastric adenocarcinoma (1); gastric cancer (1); infectious disease (1); ischemia (1); kidney cancer (1); lung carcinoma (1); lymph node metastasis (1); mammary adenocarcinoma (1); melanoma (1); meningitis (1); pancreatic ductal adenocarcinoma (1); parasite (1); spinal muscular atrophy (1).